GLI1 (GLI family zinc finger 1)
Diseases named in the same sentence as GLI1 in open-access papers (continued):
Sharing a sentence is not in itself a finding about the gene and the disease.
glioblastoma (continued). "Therefore, the combination of miR-326 and curcumin presents a promising strategy for glioblastoma treatment by increasing glioma cell chemosensitivity to curcumin, primarily through SHH/GLI1 pathway inhibition." (PMID 40227413, 2025). "Moreover, miR-9 via targeting PTCH1 and enhancing expression of GLI1 can trigger the activation of Shh cascade and affect expression of drug efflux transporters, MDR1 and ABCG2 in glioblastoma cells, therefore enhancing Temozolomide resistance in tumor cells." (PMID 36100906, 2022). "is more specifically expressed in glioblastoma than SMO and is relevant to Gli1 expression." (PMID 33446260, 2021). "For examples, GLI1 can bind to the promoter region of O6-methylguanine DNA methyltransferase (MGMT) gene to regulate the expression of MGMT and chemotherapy resistance to temozolomide in glioblastoma cells." (PMID 34659557, 2021). "GLI1 belongs to the SHH pathway and is overexpressed in glioblastoma tumors." (PMID 32429463, 2020). "Hedgehog pathway signaling activates the glioblastoma Gli1/2/3 genes (named so because they were initially identified in glioblastomas) through a complex epistatic pathway of negative regulators." (PMID 32283832, 2020). "Recently, it was shown that Akt signaling is required for maintenance of glioblastoma tumors and non-canonical activation of GLI1 was observed by PI3K/Akt signaling in renal cell carcinoma." (PMID 28380428, 2017). "Interestingly, enhanced inhibition of stem cell markers like OCT4 and Nanog, was also observed with penfluridol treatment in glioblastoma cells pretreated with GANT61, cyclopamine or GLI1 knock down using siRNA." (PMID 28380428, 2017). "Inhibition of GLI1 by established inhibitors like GANT61 or cyclopamine or knocking down GLI1 using siRNA or GLI1 CRISPR/Cas9 significantly reduced the expression of OCT4 and Nanog indicating direct regulation of cancer stem cells by GLI1 in glioblastoma cells and." (PMID 28380428, 2017). "Noncanonical GLI1 activation has been reported in esophageal, glioblastoma, and lung cancers." (PMID 38999049, 2024). "The transcriptomics data on 149 clinical cases of The Cancer Genome Atlas-Glioblastoma database showed a strong correlation between PTCH1 and GLI1 upregulated expression in GBM indicating that activation of the canonical SHH pathway might be associated with this malignancy." (PMID 36010607, 2022). "Suppression of GLI1/GLI2 functions by a C-terminus truncated GLI3 repressor mutant (GLI3R), or by GANT61, a pharmacological inhibitor of GLI1/GLI2, reduced hTERT protein expression in human colon cancer, prostate cancer and Glioblastoma multiforme (GBM) cell lines." (PMID 24086482, 2013). "Similarly, in glioblastoma, GANT61 significantly reduced the cell viability, proliferation, and migration of tumour spheroids when paired with conditioned media from reactive astrocytes, indicating the drug’s potential for tackling aggressive tumours with high GLI1 expression." (PMID 39596169, 2024). "However, it was not known whether GLI1 activation was mediated by Akt in glioblastoma." (PMID 28380428, 2017).
prostate carcinoma (59 papers, 2004 to 2025). A carcinoma that arises from epithelial cells of the prostate gland. "Recently, GLI1 was found to be significantly associated with a worse prognosis in oral, gastric, and prostatic cancer patients." (PMID 39062853, 2024). "Gli1 acts as a core mediating agent of the Hedgehog pathway that strongly associated with prognosis in prostate cancer." (PMID 38008751, 2023). "Hedgehog pathway activity (as measured by GLI1 expression) was detectable at baseline in men with localized high-risk prostate cancer." (PMID 29262631, 2017). "The GLI (GLI1/GLI2) transcription factors have been implicated in the developmentand progression of prostate cancer although our understanding of how theyactually contribute to the biology of these common tumours is limited." (PMID 21633508, 2011). "Additionally, in a low-androgen environment, both cyclopamine and siRNA directed against SMO caused downregulation of androgen-regulated genes in prostate cancer cells while administration of exogenous GLI1 allowed cell growth in an androgen-deficient medium." (PMID 26426053, 2015). "Specifically, the protein expression of DAX1 and GLI1/GLI2 in different prostatic cancer specimens should be investigated." (PMID 37504255, 2023). "This in vitro study elucidates the role of the GLI1 protein in the mechanism of tumor suppression of miR-218 in prostate cancer." (PMID 36969009, 2023). "Further, we demonstrated the potential therapeutic use of NF-κB(p65) and GLI1 inhibitors in treating two cell lines widely used as in vitro models of advanced prostate cancer." (PMID 35805202, 2022). "Tumor necrosis factor-alpha (TNFα) induced SK61 phosphorylation, which was associated with enhanced GLI1 expression and GLI1 target genes, including cell cycle regulators CCND1 and n-Myc, in prostate cancer PC3 cells." (PMID 34572373, 2021). "Another experiment in prostate cancer reveals that genistein is able to suppress Gli1 pathway in inhibiting CSC characteristics." (PMID 34769099, 2021). "It accelerates the inhibition of prostate cancer cell marker CD44 in vivo and in vitro and also downregulates the hedgehog-Gli1 pathway that contributes to the anticancer stem cell effect of genistein in prostate cancer TCs." (PMID 34336089, 2021). "We found that ISX readily induced GLI1 protein as well as Hh target genes in the human prostate carcinoma cell lines 22Rv1 and DU145." (PMID 33921042, 2021). "A similar study reveals Hedgehog signaling inhibition and subsequent Gli1 down-regulation by genistein in prostate cancer stemness suppression." (PMID 34769099, 2021). "Curcumin has been shown to regulate GLI1 mRNA and GLI1 reporter activity in prostate cancer cell lines and in vivo model and GLI1 is known to be an important transcription factor in Hedgehog pathway." (PMID 35582033, 2021). "From in vitro studies, we know that Hh-inhibitors decrease the expression of Gli1 and induce cell cycle arrest in prostate cancer cells." (PMID 32770014, 2020). "In prostate cancer, treatment with Gant61 induced suppression of tumor growth with decreased GLI1 and PTCH1 expression." (PMID 33396427, 2020). "GLI1 is an important component of the SHH (Sonic Hedgehog Signaling Molecule)-GLI signaling pathway that is positively correlated with prostate cancer severity." (PMID 32765970, 2020). "We found that expression of the hedgehog-signaling components SHH, PTCH1, and GLI1 was reduced between 30–70% in OLFM4-expressing prostate-cancer cells compared with control vector-transfected cells." (PMID 26581960, 2015). "Smoothened down-regulation did reduce GLI1 expression in LNCaP prostate cancer cells proving the efficacy of the smoothened shRNAs." (PMID 23436775, 2013). "We have previously used species-specific primers in RT-PCR analysis to demonstrate the upregulation of mouse Gli1 in mouse xenografts of human prostate carcinoma." (PMID 19254376, 2009).
prostate carcinoma (continued). "We have shown previously that Shh-expressing human prostate cancer cells upregulated Gli1 expression in surrounding tumor stroma and accelerated tumor growth in a mouse xenograft model of human prostate cancer." (PMID 19254376, 2009). "We first reported that robust Shh expression and Gli1 expression was characteristic of both the normal adult human prostate as well as benign prostatic hyperplasia and prostate cancer." (PMID 17343742, 2007). "Of note, other members of the Sonic Hedgehog pathway, namely SU(FU), GLI1 and SMOH also map to areas implicated in familial genetic studies and are up-regulated in studies of sporadic prostate cancer tumors." (PMID 16507112, 2006). "Inhibition of Perlecan expression by siRNA in prostate cancer cell lines decreases SHH signaling while expression of the downstream SHH effector GLI1 rescues the proliferation defect." (PMID 16507112, 2006). "To demonstrate the role of hedgehog pathway in prostate cancer, we screen five available cell lines for the expression of Gli1, PTCH1 and HIP." (PMID 15482598, 2004). "Gli1 promotes the progression of many types of cancers including, pancreatic and prostate cancer." (PMID 32430068, 2020). "Furthermore, inhibition of PI3K/mTOR by NPV-BEZ-235 was shown to inhibit GLI1-dependent proliferation of androgen-independent prostate cancer cells." (PMID 33081032, 2020). "In addition, mTOR/S6K1 signaling has been shown to contribute to radiotherapy-induced GLI1 activity in head and neck squamous cell carcinoma cell lines and to enhance GLI1 expression in prostate cancer cell lines." (PMID 30934935, 2019). "Gli1 has been identified as the final transcriptional effector and the key marker of the Hh signaling pathway, and has been shown to be activated in various human malignancies such as prostate cancer and gastrointestinal cancer." (PMID 27836001, 2016). "In addition, the downregulation of β1 integrin reduces the expression of Gli1 in human prostate prostate cancer cells." (PMID 27836001, 2016). "In addition, KCTD11 overexpressing prostate cancer cells displayed a reduction of cell proliferation-related genes, which are known direct targets of Hedgehog/Gli1, such as Cyclin D2 and IGF-2." (PMID 25045667, 2014). "Although the independency of Hh molecule expression on patient survival has been previously shown in bladder and prostate cancers, we are the first to reveal that of GLI1 in lung adenocarcinoma, which is indicative of the involvement of Hh signaling in a subset of NSCLC." (PMID 25103784, 2014). "Data from this study provide multiple lines of scientific evidence demonstrating a critical role of AR signaling in stromal Gli1-lineage cells in supporting prostate epithelial cell tumorigenesis, leading to the development of different therapeutic strategies for treating advanced prostate cancer." (PMID 36323713, 2022). "Several previous reports implicated the GLI-1 gene in docetaxel, methotrexate and etoposide chemoresistance through transcriptional modulation of the ABC transporter family genes in esophageal adenocarcinoma, prostate carcinoma and metastatic squamous cell carcinoma cell lines." (PMID 28978016, 2017). "In a large proportion of prostate cancers high levels of Sonic Hedgehog expression is observed along with expression of multiple members of the Hedgehog signaling pathway such as its receptor Patched1, downstream transcription factor Gli1, and intracellular modulator Hedgehog Interacting Protein." (PMID 16507112, 2006). "In prostate cancer, RCC2 enhances cell proliferation and migration via modulating Hh/GLI1 signaling pathway." (PMID 38993556, 2024). "Components of the SHH pathway, including GLI1 (GLI family zinc finger 1), PTCH1 (protein patched homolog 1), and SHH, are highly up-regulated in human prostate cancer tissues, compared with prostatic epithelium." (PMID 36969009, 2023).
prostate carcinoma (continued). "Co-immunoprecipitation assays demonstrated the physical interaction between DAX1 and GLI1/GLI2, both in exogenous overexpression systems and in endogenous protein complexes from prostate cancer cells." (PMID 37504255, 2023). "In prostate cancer cells, silencing METTL3 reduces the m6A modification of Gli1, an important component of Hedgehog pathway, and reduces the expression of Gli1, as well as the expression of downstream of hedgehog pathway, which promotes tumor cell apoptosis." (PMID 35022030, 2022). "Due to prostate cancer cells’ dependence on SHH signaling, decreased expression of GLI1 deprived prostate cancer cells of SHH signaling and forced apoptosis." (PMID 35350378, 2022). "Protein expression of the hedgehog signaling-pathway components SHH, PTCH1, GLI1, and GLI2 was also generally reduced in OLFM4-expressing prostate-cancer cells compared with control vector-transfected cells." (PMID 26581960, 2015). "In prostate cancer, the mRNA levels of SHH, PTCH1 and GLI1 were highly elevated in more advanced stages of the cancer, and all those components were closely linked to Gleason score." (PMID 25369201, 2014). "High levels of Sonic Hedgehog activity, as monitored by PTCH1, GLI1 or HIP expression, are present in all metastatic prostate cancer samples that have been tested." (PMID 16507112, 2006). "Mechanistically, PlexinD1 activates an ErbB3/cMet-ERK/AKT-noncanonical Hh/Gli1 signaling cascade to facilitate prostate cancer growth and plasticity." (PMID 39748059, 2025). "Indeed, targeting Hh signaling at the SMO level, with an SMO antagonist, and at the GLI1 level, with DAX1 activation, should result in a more potent inhibition of prostate cancer growth." (PMID 37504255, 2023). "METTL3 positively regulates prostate cancer cell proliferation and metastasis through GLI1 rather than other components of the SHH cascade in an m6A modification-dependent manner, while the underlying mechanism remains to be investigated further." (PMID 37149646, 2023). "Interestingly, DAX1 overexpression significantly inhibited Hh signaling by reducing GLI1 and GLI2 activity, prostate cancer cell proliferation, and viability." (PMID 37504255, 2023). "Furthermore, knockdown of Mettl3 decreased expression of GLI1, a component of the Sonic hedgehog (SHH) signaling pathway, which prostate cancer cells are dependent on for survival." (PMID 35350378, 2022). "Several clinical studies showed that the downregulation of intratumoral GLI1 levels did not correlate with tumor response in pancreatic and prostate cancer patients treated with SMO inhibitors." (PMID 34572373, 2021). "GLI1 is a negative modulator of the androgen receptor and contributes to the androgen-independent growth of prostate cancer." (PMID 32765970, 2020). "Additionally, in the 72 prostate cancer sample dataset (GEO accession: GSE56916), FOXS1 expression also strongly correlates (r = 0.439, P < 0.0001) with GLI1 expression." (PMID 30098229, 2018). "In this study GANT61 abrogated GLI function in the nucleus, blocked both GLI1- and GLI2- mediated transcription, inhibited GLI1-DNA binding, and demonstrated anti-tumor activity against human prostate cancer xenografts." (PMID 24962990, 2014). "Similarly, blocking HH/GLI signaling in the prostate cancer cells C4-2, DU145 and PC3 also demonstrated decreased GLI1, GLI2 and hTERT protein expression." (PMID 24086482, 2013). "Upregulation of PlexinD1 activates the ErbB3/cMet-ERK/AKT-noncanonical Hedgehog/Gli1 signaling to promote aggressiveness, invasiveness, and therapy resistance of metastatic castration-resistant prostate cancer cells, which can be blocked by the PlexinD1-targeted protein inhibitor D1SP." (PMID 39748059, 2025). "Interestingly, the authors found that the protein levels of GLI1 and GLI2 were highly increased in the androgen-independent prostate cancer cell lines PC3 and DU145 but not in the androgen-dependent cancer cell line LNCaP." (PMID 33081032, 2020).
prostate carcinoma (continued). "We found that all Gli1 positive cells (n = 500) were TUNEL negative, supporting our hypothesis that down-regulation of Gli1 may be an important mechanism by which cyclopamine mediates apoptosis in prostate cancer cells with activated hedgehog signaling." (PMID 15482598, 2004).
basal cell carcinoma (56 papers, 2004 to 2025). A carcinoma involving the basal cells. "This mutation, from a drug-resistant basal cell carcinoma patient, dramatically diminished GLI1–SUFU binding (Kd = 3,800 ± 1,600 nM, a ∼250-fold decrease in affinity)." (PMID 35831023, 2022). "These mutations were chosen from those documented in the COSMIC (catalog of somatic mutations in cancer) database, as well as from mutations found from targeted sequencing of the GLI1 gene in advanced or drug resistant basal cell carcinomas." (PMID 35831023, 2022). "Because loss-of-function mutations in the tumor suppressor PTCH1 cause elevated GLI1 expression in a large proportion of basal cell carcinomas, we tested whether the P681L mutation altered PTCH1 function." (PMID 24368541, 2013). "GLI1, a mediator of the Hh signalling pathway has previously been implicated in the development of different human tumour entities such as oesophageal squamous cell carcinomas, basal cell carcinomas and brain tumours." (PMID 19706168, 2009). "We determined whether GLI1 polymorphisms were risk factors for developing basal cell carcinoma, either alone or in combination with patterns of past sun exposure, and whether there were functional differences among different GLI1 haplotypes." (PMID 19948058, 2009). "The combination therapy of HDAC1 and aPKC inhibitors has been shown to prevent GLI1 nuclear maturation and effectively antagonize basal cell carcinoma (BCC) at lower doses than either agent alone." (PMID 38498906, 2024). "On the other hand, silencing the NLRP1 and NLRP3 gene changed the expression of these squamous cell carcinoma proteins marker genes as well as basal cell carcinoma proteins such as Gli1, Gli2, FOXO3A." (PMID 39839625, 2024). "Somatic SUFU mutations have also been found in various cancers, including sporadic basal cell carcinomas, where they have been shown to inappropriately enable GLI1-driven transcription." (PMID 35831023, 2022). "A recent study showed that overexpression of DSG2 induced STAT3 phosphorylation and further increased Gli1 levels in basal cell carcinomas." (PMID 32095325, 2020). "In the basal cell carcinoma pathway, 11 up-regulated genes, including GLI1, PTCH1, and SHH, were identified." (PMID 30770723, 2019). "PKCι was shown to phosphorylate and activate Gli1, a transcription factor involved in Hh signaling in basal cell carcinoma cells." (PMID 30214681, 2018). "Glioma-associated oncogene 1 (GLI1) is a transcription factor that functions at the end of the Hedgehog signaling pathway, and its upregulation is associated with basal cell carcinoma in mice and cerebellar tumor formation in humans." (PMID 27999332, 2016). "We therefore sought to determine if GLI1 played a role in Ewing tumors much like the role it plays in basal cell carcinoma." (PMID 23365673, 2013). "We analyzed probe-level expression values to account for alternative transcription of GLI1, previously reported for Hedgehog pathway activity in basal cell carcinoma." (PMID 24223768, 2013). "GLI1 genotypes at c.2798 and c.3298 from 201 basal cell carcinoma patients were compared to 201 age and sex-matched controls." (PMID 19948058, 2009). "We have shown that Gli1 down-regulation is necessary for cyclopamine-mediated apoptosis in basal cell carcinoma cells." (PMID 15482598, 2004). "Similarly, RhoA/ROCK is controlled by the TRPV4 channel and the activation of RhoA/ROCK has been shown to regulate downstream signaling transcription factors including Stat3 and Gli1 in amoeboid cancer cells and basal cell carcinomas, respectively." (PMID 40682198, 2025). "Interestingly, in the cilia-retaining Hedgehog-dependent tumour basal cell carcinoma, PKCι is upregulated by Hedgehog signalling and potentiates the Hedgehog pathway via GLI1 phosphorylation." (PMID 39168978, 2024).